hsa-mir-423 (hsa-mir-423 )
Gene: Long non-coding RNA gene on chromosome 17 (30,117,079 to 30,117,172, reverse strand). Ensembl gene ENSG00000266919.
Gene Ontology:
Biological process: miRNA-mediated post-transcriptional gene silencing
Cellular component: RISC complex
Homologues: Orthologues: mouse Mir423 (67% identical), pig ssc-mir-423 (61% identical).